IL1B (interleukin 1 beta)
Diseases named in the same sentence as IL1B in open-access papers (continued):
Sharing a sentence is not in itself a finding about the gene and the disease.
periodontitis (continued). "As a pro-inflammatory cytokine, IL-1β participates in inflammation, immune regulation and bone resorption in periodontitis." (PMID 31900383, 2020). "A mathematical model was constructed to identify Grade C periodontitis patients based on the subjects’ GCF levels of IL-1β and IL-9, which achieved an area under the receiver-operating characteristic (ROC) curve of 0.94." (PMID 33218047, 2020). "In order to better acknowledge the expression of each component of NLRPs inflammasome as well as IL-1β in the process of periodontitis, clinical samples from patients with periodontitis were analyzed in this study." (PMID 32903638, 2020). "Despite the similar clinical improvement in response to non-surgical periodontal treatment, moderate pockets of grade C periodontitis patients still presented higher IL-1β and lower IL-9 GCF levels." (PMID 33218047, 2020). "Translating these data into clinic, it is well known that TNF-α, IL-1β and IFN-γ are abundant in periodontitis-associated lesions and are involved in the destructive immune response and in pathogenic alveolar bone remodeling during periodontitis." (PMID 33339125, 2020). "This degradation is induced by proinflammatory cytokines such as IL-1β and TNFα, suggesting that these enzymes play an important role in the pathogenesis of periodontitis." (PMID 33294463, 2020). "It has been reported that bortezomib inhibits the expression of IL-1β and prevents alveolar bone absorption in experimental periodontitis." (PMID 31900383, 2020). "Here, for the first time, we confirmed a protective effect of P. atlantica kurdica gel against bone loss in induced periodontitis by the down regulation of RANKL and IL-1β markers through ELISA analysis." (PMID 33321702, 2020). "Several previous meta-analyses bring results on the possible association among polymorphisms in IL1A, IL1B, IL6, IL10 and IL17A/F genes and diverse clinical aspects of periodontitis, as well as dental implant failure." (PMID 32075624, 2020). "IL-1β is found at higher concentrations in the GCF of patients with periodontitis compared to healthy controls." (PMID 32183255, 2020). "Peripheral neutrophils secrete excessive IL-1β, IL-8, IL-6, and tumor necrosis factor-α in patients with periodontitis." (PMID 32698486, 2020). "Patients with severe periodontal disease had higher levels of TNF-α in the blood circulation, and the cytokines TNF-α, IL-6 and IL-1β are insulin antagonists, which play an important role in the pathogenesis of periodontitis." (PMID 32634783, 2020). "Our findings demonstrated that NLRP3 inflammasome and IL-1β were both highly expressed in human gingival tissues with severe chronic periodontitis." (PMID 32903638, 2020). "In previous studies, PG-LPS was shown to be a major pathogenic factor of chronic periodontitis that stimulates PDL cells to produce pro-inflammatory factors, such as TNF-α and IL-1β, causing the destruction of the alveolar bone." (PMID 33287198, 2020). "The sensitivity and specificity of predicting periodontitis on the basis of IL-1β and PGE2 levels were also reported." (PMID 33383828, 2020). "For example, exenatide decreased the periodontitis-induced inflammatory gene expression of IL-1β, iNOS, and matrix metalloproteinase-9 (MMP-9) in the gingiva." (PMID 33274238, 2020). "Clinical evidence verifies that periodontitis leads to excessive IL-1β production locally (GCF and saliva) and systemically (serum)." (PMID 31900383, 2020). "The CatB expression is upregulated in the macrophages which involves the production of IL-1β and amyloid β in gingival tissues of the patients with periodontitis." (PMID 32328131, 2020). "A case-control study that monitored salivary IL1β in periodontitis patients before and after phase I treatment showed a significant difference in the level of IL1β between healthy controls and a periodontitis group at baseline." (PMID 33081038, 2020).
periodontitis (continued). "The biomarkers that decreased after SRP and OHI in periodontitis patients were IL-1β, MMP-8, MMP-9, PGE2, and TIMP-2." (PMID 33383828, 2020). "Roles of inflammatory cytokines such as interleukin (IL)-1β and IL-6 in periodontitis have been explored by targeting fibroblasts, epithelial cells and macrophages." (PMID 31968635, 2020). "The review focuses on the production, mechanism, present treatments and future potential strategies for IL-1β in periodontitis." (PMID 31900383, 2020). "During the inflammatory process that takes place in periodontitis, a significant increasing of the expression of interleukins, such as IL-1β, IL-6 or transforming growth factor (TGF-1β), which plays a fundamental role, occurs." (PMID 31963913, 2020). "In recent decades, the production of IL-1β and pyroptotic processes has been studied in the field of periodontitis." (PMID 31900383, 2020). "Recent studies have found higher expression of IL-1β as well as NLRP3 inflammasomes in gingival tissues of periodontitis compared to healthy tissues, which is consistent with our findings in gingival tissue samples." (PMID 32903638, 2020). "IL1B [+3954; rs1143634], which is part of the IL1 genotype previously associated with periodontitis, is among the variants associated with high gingival crevicular fluid‐interleukin‐1β." (PMID 31850638, 2020). "The polymorphisms in NLRP3, IL1B and IL2 genes influence the development of periodontitis, independently of smoking habits." (PMID 31978095, 2020). "The degree of suppression of IL8, IL1B, CCL2, CCL5, MMP3, and COX2 caused by I-BET151 or JQ1 in P. gingivalis-infected GFs from periodontitis patients was comparable to that observed in healthy donor GFs." (PMID 31114581, 2019). "IL-37 probably increased due to elevated IL-1β cytokine levels in the inflamed periodontal tissues prior to aggressive periodontitis treatment." (PMID 31308830, 2019). "Periodontitis is a prevalent chronic inflammatory disease due to the host response (IL-1β, IL-6, TNF-α and IL-17A) to oral bacteria such as Porphyromonas gingivalis." (PMID 31848404, 2019). "Pivotal inflammatory cytokines in periodontitis, namely IL-1β, IL-6, TNF-α and IL-17A, mediate both periodontal inflammation and alveolar bone resorption." (PMID 31848404, 2019). "Statins were shown to suppress inflammatory factors associated with periodontitis such as IL-6, TNF-α, IL-1β, as well as periodontal pathogens Pg and Aa." (PMID 31196047, 2019). "The main outcome of this investigation is that the PBMCs of periodontitis patients secreted higher levels of IL-1β, both spontaneously and when exposed to H2S, as compared to healthy controls." (PMID 31164964, 2019). "In our experiments, the IL-1β and IL-6 expression in gingival epithelia was elevated in all periodontitis mice compared with their normal controls." (PMID 31691738, 2019). "IL-4 suppress the production of IL-17 and IL-1β, which play an important role in the periodontitis pathogenesis and inhibit both Th1 pro-inflammatory response and bone resorption." (PMID 31035477, 2019). "The levels of proinflammatory cytokine IL-1β, which plays a role in the pathogenesis of aggressive periodontitis, were shown to be positively correlated with the IL-37 levels." (PMID 31308830, 2019). "LPS can induce the NF-κB signaling pathway activation to generate M1-related cytokines such as IL-6, TNF-α, IL-1β, and nitric oxide (NO) in macrophages during the progression of periodontitis." (PMID 31022963, 2019). "In the same context, a higher expression of IL-1β was observed in gingival fluid from deeper sites of periodontitis patients." (PMID 31049022, 2019). "Unexposed cells from periodontitis patients secreted higher levels of IL-1β compared to the healthy controls (p = 0.0001)." (PMID 31164964, 2019). "In periodontitis, there is an increase in the production of proinflammatory mediators, such as IL-1β, TNF-α, IL-6, IFN-γ, and the levels of acute-phase proteins, such as CRP." (PMID 35919481, 2019).
periodontitis (continued). "In particular, they produce pivotal pro-inflammatory cytokines in periodontitis such as IL-1β, IL-6 and TNF-α in response to bacterial challenge with the key periopathogen P. gingivalis through the NFκB and MAPK signaling pathways." (PMID 31848404, 2019). "The NLRP3 inflammasome and its effector molecules (IL-1β and caspase-1) play roles in the development of periodontitis." (PMID 31341421, 2019). "Previous research has shown the important role of IL-1β in the host defense against bacterial infections and the pathogenesis of periodontitis." (PMID 31691738, 2019). "In the present study, we analyzed the levels of IL-1β, and an anti-inflammatory cytokine IL-37 in the GCF samples of periodontitis patients before and after treatment, and their association with other clinical parameters." (PMID 31308830, 2019). "This was confirmed by the reduced expression of TNF and IL-1β in the gingiva of animals with specific-deletion of Dkk-1 in osteocytes submitted to periodontitis." (PMID 31921182, 2019). "For example, the IL-1β concentration changes in GCF suggest these cytokines as a predictable marker of gingival inflammation in chronic periodontitis patients." (PMID 29966238, 2018). "Canakinumab is a human monoclonal antibody that neutralizes IL-1β, an inflammatory protein that is elevated in states of systemic inflammation and during periodontitis." (PMID 29986441, 2018). "Our data indicated both the mRNA and protein level of IL-1b was significantly decreased in the gingival tissues of rhIL-37b IP group in the ligature induced periodontitis model." (PMID 30206230, 2018). "The level of Il-1β and Tnf-α in the gingiva of type 1 diabetes patients with periodontitis is also elevated." (PMID 30439990, 2018). "RA patients with periodontitis on DMARDs have been found to exhibit lower local IL-1β, IL-4, and TNF-α levels than otherwise healthy patients with periodontitis, however, the study about the effect of DMARDs on clinical periodontal parameters is limited." (PMID 30211216, 2018). "An in vitro study proved that gingival fibroblasts from periodontitis patients expressed more IL-1β compared with the gingival fibroblasts from healthy subjects." (PMID 29922598, 2018). "Several genes downstream of IL-1β that have been identified in gingival fibroblasts are involved in periodontitis development." (PMID 29932110, 2018). "Interleukin-1β (IL-1β) plays an important role as a mediator of various inflammatory responses in chronic periodontitis." (PMID 30647799, 2018). "Particularly, IL-1β is known to be a major mediator of periodontitis, and triggers the pro-inflammatory cytokines, IL-6 and IL-8, in gingival fibroblasts and PDLFs." (PMID 30142971, 2018). "Periodontal diseases are caused by gram-negative bacterial infections and pro-inflammatory cytokines, including IL-6, IL-8, and IL-1β, which appear to be major mediators of inflammation in periodontitis." (PMID 29932110, 2018). "A previous study showed that the amount of IL-1β mRNA expression is much higher in a group affected by chronic periodontitis than in the control group." (PMID 30647799, 2018). "It suggested that caspase-1 and pyroptosis is important in producing and releasing IL-1β in periodontitis." (PMID 29184853, 2017). "This view does not preclude the possibility of occasional instances of high‐local disease activity as evidenced by high levels of il‐1β in deep pockets of patients with aggressive periodontitis." (PMID 29744180, 2017). "In this regard Teles (2010) reported increased values of pro-inflammatory cytokines such as IL-1β in GCF of patients with periodontitis." (PMID 29299075, 2017). "Inflammatory biomarkers, such as IL-1β, IL-6, and IL-8, MMP-8, TIMP-1 and TNF-α associated with oral diseases: dental caries, gingivitis and periodontitis have been detected in saliva." (PMID 28117682, 2017).
periodontitis (continued). "The findings of this study show that IL-1β gene expression among those patients with periodontitis (excluding smoking cigarette) is significantly higher than normal individuals." (PMID 29299075, 2017). "The aim of this study is to investigate the effect of hypoxia on caspase-1 activation, IL-1β maturation, and a possible mechanism of hypoxia formation during periodontitis." (PMID 29184853, 2017). "In periodontitis, the periodontopathic pathogen, A. actinomycetemcomitans, has been involved in caspase-1 activation and secretion of IL-1β and IL-18 in the monocytes/macrophages." (PMID 29184853, 2017). "An increase (p <0.01) of IL-1β production in the periodontitis (P) group was observed when compared to the basal group (B)." (PMID 29145431, 2017). "Nal-P-113 exhibited protective effects on Porphyromonas gingivalis-induced periodontitis in rats by limiting the amount of bacteria and modulating IL-1β and TNF-α production." (PMID 28851350, 2017). "The results of different studies concerning the effects of cigarette on IL-1β level in individuals with periodontitis are controversial." (PMID 29299075, 2017). "As Rawlinson suggested, that reduced levels of IL-1β in GCF of smoking patients with periodontitis are probably related to tissue receptors." (PMID 29299075, 2017). "Previous studies in humans have shown that elevated levels of some cytokines, such as IL-1β, IL-6, IL-21, and IL-23, are necessary for promoting Th17 differentiation and maintenance during the destructive phase of periodontitis." (PMID 28497028, 2017). "In this study, we examined the expressions of NLRP3, cleaved-caspase-1 (active), and IL-1β expression, each of which were upregulated in human periodontitis gingival tissue, compared to health gingiva." (PMID 29184853, 2017). "A study on ≥30-year-old participants with periodontitis also reported that the mean IL-1β concentration was higher in smokers (706 pg/mL) than in non-smokers (612 pg/mL)." (PMID 27274336, 2016). "Higher levels of IL-1β are detected in the gingival crevicular fluid (GCF) in sites affected by periodontitis, relative to GCF from healthy sites." (PMID 27632566, 2016). "Serum levels of proinflammatory cytokines was also measured before periodontitis induction and they were higher in rats with dHPT (15.75 ± 0.49 vs. 10.12 ± 0.92 pg/m, for IL-1β and 176.75 ± 23.06 vs. 13.02 ± 1.38 pg/mL for TNF-α, p < 0.001)." (PMID 27617985, 2016). "In a periodontitis-induced Sprague-Dawley rat model, GH was able to reduce 21.26% of plasma IL-1β and 81.27% of tissue IL-1β, suggesting the potential of GH in periodontal disease treatment." (PMID 29083367, 2016). "In the GCF, the background levels of both IL-1β and IL-6 were highly and equally elevated, while IL-10 values were decreased in the periodontitis groups as compared to healthy controls." (PMID 26977121, 2016). "In a model of experimental periodontitis, TNFR1 deficiency also resulted in a higher bacterial load, decreased proinflammatory cytokine expression such as IL-1β, and reduced polymorphonuclear leucocytes recruitment." (PMID 27057100, 2016). "Several studies have suggested that IL-1β levels can be used as a good biomarker to differentiate between healthy and chronic periodontitis sites." (PMID 28074077, 2016). "Here, we show for the first time that interleukin-1β (IL-1β) has dual roles in the osteogenesis of PDLSCs at concentrations ranging from physiologically healthy levels to those found in chronic periodontitis." (PMID 27415426, 2016). "IL-1β, a potent osteotropic cytokine, plays a role in degrading the extracellular matrix in periodontitis." (PMID 27058519, 2016). "Gingival crevicular fluid (GCF) of periodontitis sites exhibits a significantly greater total amount of GPx, lactoferrin, myeloperoxidase and interleukin-1beta (IL-1β) than healthy sites." (PMID 26805896, 2016).
periodontitis (continued). "We recently found that the levels of IL-1β and inflammasome components increased in periodontitis patients and P. gingivalis induced IL-1β release via TLR2/TLR4-NLRP3/AIM2 inflammasome-caspase-1 pathway activation." (PMID 27386246, 2016). "In this study, significant correlations were also observed between salivary IL-6 and IL-1β (r = 0.72 and P < 0.01) of patients with periodontitis." (PMID 25884025, 2015). "They reported the application of the LOC system for the multiplex measurement of three salivary biomarkers, C-reactive protein, MMP-8, and IL-1β, which are related to the clinical expression of periodontitis." (PMID 26389079, 2015). "Both naproxen and ATB-346 inhibited the increase of gingival IL-1β and IL-6 secondary to periodontitis, but IL-10 was unaffected." (PMID 25755876, 2015). "A recent meta-analysis reported that type 2 diabetes patients with chronic periodontitis were found to have significantly higher GCF levels of IL-1β than their systemically healthy counterparts." (PMID 26211001, 2015). "TNF-α, a cytokine with some functions similar to those of IL-1β, has been detected at sites affected by periodontitis TNF-α and IL-1β act synergistically to initiate the cascade of inflammatory mediators." (PMID 25888355, 2015). "The β values of IL-1β and IL-6 were 2.04 and 0.34, respectively, indicating that these 2 proinflammatory cytokines significantly increased with the severity of periodontitis." (PMID 25884025, 2015). "For predicting periodontitis treatment outcomes, scaling-stimulated IL-1β is a superior biomarker than pretreatment salivary IL-1β." (PMID 25884025, 2015). "It is noteworthy that during the progression of experimental periodontitis, high levels of IL-1β and TNF-α have been positively related to RANKL expression." (PMID 24719884, 2014). "IL-6 showed higher concentrations in the serum (about 95 pg/mL) than IL-1β in the LPS-periodontitis rats, and, again, CMC 2.24 appeared to reduce the level of this cytokine." (PMID 25104884, 2014). "For both LPSs, a significantly higher stimulation of IL-1β production was found in patients with moderate chronic periodontitis compared to the other groups (p = 0.002), indicating a higher activation of innate immunity in moderate chronic periodontitis." (PMID 25299619, 2014). "In this regard, MMP-8 seems to be a better biomarker of periodontitis than other markers such as IL-1β." (PMID 24944840, 2014). "This study aimed at evaluation of pro-inflammatory cytokine response (TNF-α, IL-1β and IL-17) in patients with chronic periodontitis administered per os with a probiotic strain of Lactobacillus reuteri." (PMID 24509697, 2014). "It was found that the levels of MMP-8, MMP-9, OPG, and IL-1β declined significantly after treatment in volunteers with moderate to severe periodontitis." (PMID 24944840, 2014). "When stimulating peripheral blood mononuclear cells (PBMCs) with lipopolysaccharide, a higher IL-1β release was found in patients with moderate chronic periodontitis compared to the other groups (p<0.01)." (PMID 25299619, 2014). "CBD treatment inhibits the progression of periodontitis that was accompanied by a decrease in neutrophil migration, expression of bone related molecules and production of IL-1β and TNF-α." (PMID 25517414, 2014). "Tissue destruction in periodontitis results from the inflammatory response to the microbial products and cytokines including IL-1β and TNF- α." (PMID 25587321, 2014). "We first examined destruction of periodontal connective tissues in adult PTPα+/+ and PTPα−/− mice subjected to ligature-induced periodontitis, which increases the levels of multiple cytokines, including IL-1β." (PMID 23940616, 2013). "In a different approach, the exogenous application of recombinant human IL-1β in a rat ligature induced periodontitis model accelerated alveolar bone destruction and inflammation over a two-week period." (PMID 24151615, 2013).